FAM76B (family with sequence similarity 76 member B)
Description:
Negatively regulates the NF-kappa-B-mediated inflammatory pathway by preventing the translocation of HNRNPA2B1 from the nucleus to the cytoplasm. Inhibits the PI3K/Akt/NF-kappa-B pathway-mediated polarization of M1 macrophages by binding to and stabilizing PIK3CD mRNA, resulting in increased levels of PIK3CD protein and increased levels of phosphorylated downstream target AKT which leads to decreased NF-kappa-B signaling.
Synonyms: MGC33371
Tractability: PROTAC: ubiquitination databases record sites on it; its protein half-life has been measured.
Gene: Protein-coding gene on chromosome 11 (95,768,953 to 95,790,409, reverse strand). Ensembl gene ENSG00000077458.
Subcellular location: Nucleus speckle
Subcellular location (Human Protein Atlas): Nucleoplasm; Nucleoli fibrillar center
Gene Ontology:
Molecular function: protein binding
Biological process: mRNA stabilization; negative regulation of inflammatory response; negative regulation of macrophage activation; negative regulation of protein export from nucleus
Cellular component: nuclear speck
Genetic constraint (gnomAD): Loss-of-function variants: 15 observed, 44.8 expected, observed/expected ratio (o/e) 0.33, 90% interval 0.22 to 0.52. The upper end of that interval is the gene's LOEUF score, 0.52, which puts it in group 2 of 6, group 1 being the genes least tolerant of losing a copy. Missense variants: 331 observed, 385.72 expected, observed/expected ratio (o/e) 0.86, 90% interval 0.78 to 0.94. Synonymous variants: 158 observed, 128.05 expected, observed/expected ratio (o/e) 1.23, 90% interval 1.08 to 1.41.
Homologues: Orthologues: chimpanzee FAM76B (99% identical), macaque FAM76B (99% identical), guinea pig FAM76B (99% identical), pig FAM76B (99% identical), mouse Fam76b (98% identical), tropical clawed frog fam76b (94% identical), dog FAM76B (92% identical), rat Fam76b (89% identical), zebrafish fam76b (87% identical), rabbit FAM76B (86% identical), Drosophila melanogaster CG4452 (40% identical), Caenorhabditis elegans K04F10.7 (29% identical). Paralogues in human: FAM76A (67% identical), SENP8 (9% identical).
Diseases named in the same sentence as FAM76B in open-access papers:
FAM76B is named in the same sentence as 14 diseases in open-access papers, as found by Europe PMC text mining. Sharing a sentence is not in itself a finding about the gene and the disease. The quoted sentences say what the papers report.
Alzheimer disease (1 paper, 2023). A progressive, neurodegenerative disease characterized by loss of function and death of nerve cells in several areas of the brain leading to loss of cognitive function such as memory and language. "Hence, we evaluated the role of FAM76B in the common neurodegenerative diseases Alzheimer’s disease (AD), frontotemporal lobar degeneration with tau pathology (FTLD-tau), and frontotemporal lobar degeneration with TAR DNA-binding protein 43 inclusions (FTLD-TDP)." (PMID 37643469, 2023).
brain injury (1 paper, 2023). Acute and chronic (see also brain INJURIES, CHRONIC) injuries to the brain, including the cerebral hemispheres, CEREBELLUM, and brain STEM. "We further showed that FAM76B suppressed inflammation in vivo using a traumatic brain injury (TBI) mouse model." (PMID 37643469, 2023).
colitis (1 paper, 2024). Inflammation of the colon. "In the DSS-induced colitis model, we found that Fam76b knockout mice with DSS-induced colitis had more pronounced symptoms of colitis than wild-type mice with DSS-induced colitis, indicating that the loss of FAM76B exacerbates the severity of experimental colitis in mice." (PMID 38421448, 2024). "The expression of p110δ and p-Akt in the colon tissue of Fam76b knockout mice with colitis was decreased." (PMID 38421448, 2024). "The results revealed that the quantity of F4/80+ p110δ+ macrophages in the colonic tissue of Fam76b knockout mice with colitis was significantly lower than that in wild-type mice with colitis." (PMID 38421448, 2024). "Moreover, the function of FAM76B in inhibiting M1 macrophage polarization to protect against IBD was further demonstrated in a Fam76b knockout experimental colitis mouse model." (PMID 38421448, 2024). "Therefore, we next explored the influence of FAM76B on DSS-induced experimental colitis in mice in vivo." (PMID 38421448, 2024). "Fam76b knockout reduced the stability of PIK3CD mRNA, then regulated the PI3K/Akt/NF-κB pathway, promoted M1 macrophage polarization, and led to Fam76b knockout mice being susceptible to DSS-induced experimental colitis." (PMID 38421448, 2024). "However, the colon of Fam76b knockout mice with colitis showed significantly more inflammatory cell infiltration and histological damage compared with wild-type mice with colitis." (PMID 38421448, 2024). "Moreover, more inflammatory cell infiltration and more severe epithelial damage were observed in the colon tissues of Fam76b knockout mice with colitis in comparison to wild-type mice with colitis." (PMID 38421448, 2024). "To further investigate whether the severity of colitis in Fam76b knockout mice was related to the upregulated M1 macrophage polarization caused by FAM76B, we detected the expression of NOS2 in the colonic tissues of wild-type and Fam76b knockout mice with colitis." (PMID 38421448, 2024).
inflammatory bowel disease (1 paper, 2024). A spectrum of small and large bowel inflammatory diseases of unknown etiology. "Finally, FAM76B was proven to protect against inflammatory bowel disease (IBD) by inhibiting M1 macrophage polarization through the PI3K/Akt/NF-κB pathway in vivo." (PMID 38421448, 2024).
cancer (1 paper, 2012). A tumor composed of atypical neoplastic, often pleomorphic cells that invade other tissues. "The other genes upregulated belonged mainly to the “cancer” and cell death functions (NFAT5, BMO2K, DLST, IL6ST, FAM76B, and MGA)." (PMID 22619672, 2012).
neurodegenerative disease (1 paper, 2023). A disorder of the central nervous system characterized by gradual and progressive loss of neural tissue and neurologic function. "The results suggested that FAM76B mediated neuroinflammation via influencing the translocation of hnRNPA2B1 in vivo during TBI repair and neurodegenerative diseases." (PMID 37643469, 2023). "Lastly, FAM76B was shown to interact with hnRNPA2B1 in human tissues taken from patients with acute, organizing, and chronic TBI, and with different neurodegenerative diseases." (PMID 37643469, 2023).
FAM76B also shares sentences with these, for which no sentence is quoted: autoimmune thyroid disease (1 paper); basal cell carcinoma (1); frontotemporal lobar degeneration (1); hypothyroidism (1); multiple sclerosis (1); rheumatoid arthritis (1); tumor (1); vitiligo (1).